CTLA4 (cytotoxic T-lymphocyte associated protein 4)
Diseases named in the same sentence as CTLA4 in open-access papers (continued):
Sharing a sentence is not in itself a finding about the gene and the disease.
tumor (continued). "mAbs against PD-1/PD-L1 and CTLA-4 have become powerful tools to release the inhibitory regulation of T-cell activation from tumor cells or the tumor microenvironment (TME)." (PMID 35795050, 2022). "Early trials of combination therapy of anti-TIM-3 and anti-TIGIT antibodies with PD-1 or CTLA-4 in a variety of tumor types are also ongoing and need further exploration." (PMID 35541908, 2022). "The direct role of A2AR and TIM3 in regulating CTL—tumor cell interaction thus generates a promising contrast to PD-1 and CTLA-4." (PMID 35013519, 2022). "saw an increase in CTLA-4 expression amongst CD8+TIL in CAF rich tumours using RNA sequencing and flow cytometry." (PMID 35479076, 2022). "The anti-tumor response induced by these antibodies and their ability to deplete intra-tumoral Tregs was superior to ipilimumab in human CTLA4 knock-in mouse models." (PMID 35326731, 2022). "PD-1 plus CTLA-4 inhibitors promote the anti-tumor immune response through different complementary mechanisms that affect different signaling pathways." (PMID 35000616, 2022). "CTLA-4 is constitutively expressed in tumor-infiltrating Tregs, while it is only expressed in low amounts of the surfaces of circulating Tregs and lymphoid organs." (PMID 36588722, 2022). "Our study found that tumor samples in the high-risk group expressed higher levels of BRCA1 and BRCA2 but lower levels of CTLA4 and PDCD1." (PMID 36704358, 2022). "A triple combination of chidamide + celecoxib + anti-CTLA-4 antibody significantly reduced tumor volume, with primary tumor eradication in 6 out of 8 mice, and 100% survival at day 60 after tumor implantation." (PMID 35058524, 2022). "In preclinical studies, blockade of CTLA-4 with antibodies against CTLA-4 enhanced the anti-tumor immunity by rejuvenating cytotoxic T-cells activity and also enhanced the response of tumors to high-dose hypofractionated irradiation." (PMID 35805044, 2022). "When combined with anti-cytotoxic T lymphocyte antigen-4 (CTLA4), the remaining tumor cells in mice were attacked, contributing to restraining metastasis." (PMID 35745800, 2022). "TLR7 agonists in combination with checkpoint inhibitors targeting PD-1 and CTLA-4 have been shown to be safe and effective in immunotherapy-resistant tumor models to promote more long-term immune responses." (PMID 36389785, 2022). "Mice were implanted with both tumors (Panco02.SMG1KD and Panc02.gCtrl) expressing similar levels of luciferase and SIINFEKL and treated with anti-PD-1 and anti-CTLA-4 at days 1, 4 and 7 post tumor inoculation." (PMID 36443756, 2022). "Immune checkpoint blockade (ICB) therapy, using monoclonal antibodies targeting immune-inhibitory receptors like PD-1/PD-L1 and CTLA-4, seeks to reactivate the impaired T-cell response against tumor." (PMID 35558087, 2022). "Monoclonal antibodies blocking the binding of the immune checkpoint molecules PD-1 and CTLA-4 to the ligands can restore exhausted T cell immunity against tumors, leading to the suppression of tumor growth." (PMID 35514996, 2022). "Sensitivity of tumor models to immunotherapy is also associated with the tumor location, probably due to the orthotopic microenvironment, in which tumors exhibited a low response to immune checkpoint blockades (both PD1 and CTLA4 blockade)." (PMID 35874730, 2022). "The therapeutic blockade of the CTLA-4 and PD-1/PD-L1 pathways promotes the activation of tumor-specific T cells resulting in tumor rejection." (PMID 35043373, 2022). "CTLA-4 is a transmembrane glycoprotein receptor expressed on Tregs and memory T cells, which suppresses anti-tumor immunity by engaging CD80/86 on DCs." (PMID 35433427, 2022). "In human CD4+ T cells, miR-138 represses PD-1, CTLA-4, and FoxP3 expression, and in vivo administration of miR-138 mimics to tumor-bearing mice led to enhanced T-cell–mediated tumor immunity and survival." (PMID 36248881, 2022).
tumor (continued). "CPI-444, an A2AR antagonist, combined with immune checkpoint blockade antibodies (PD-L1 and CTLA-4), significantly reduces the rate of tumor growth by improving T-cell anti-tumor immune responses." (PMID 36231064, 2022). "And several potential immunotherapeutic targets including PD-L1, NY-ESO-1, B7-H3, and CTLA-4 showed their potential for the anti-tumor therapies in clinical settings." (PMID 36538194, 2022). "PDCD1 exhibited high expression in exhausted CD8+ T cells (CD8-C4), and suppressive tumor Tregs highly expressed CTLA4." (PMID 34793335, 2022). "When inhibitory receptors such as PD-L1 and CTLA-4 on the surface of tumour cells are expressed in large numbers, they can deprive T cells of their tumour cell-killing activity, thus enabling immune escape of tumour cells." (PMID 36211409, 2022). "In particular, the recent development and clinical application of cytotoxic T lymphocyte-associated antigen-4 (CTLA-4) and programmed cell death protein-1/ligand-1 (PD-1/PD-L1) immune checkpoint inhibitors once brought a new era of tumor treatment." (PMID 36713427, 2022). "Inhibition of TMEM176B by the 1,4-dihydropyridine derivative BayK8644 triggers inflammasome-dependent tumor control and improves the efficacy of immune checkpoint blockers, such as anti-CTLA4 and anti-PD-1 monoclonal antibodies." (PMID 35884428, 2022). "By blockade of PD-1/PD-L1 and CTLA4, immune checkpoint inhibitors can mitigate the suppressive effect on immune cells within the tumor immune microenvironment and enhance endogenous anti-tumor immunity." (PMID 36091778, 2022). "After exposure to E.G7-OVA tumor cells, mice were both immunized with vaccine expressing ovalbumin and treated with anti-CTLA-4." (PMID 35620336, 2022). "Following stimulation of immune cells with tumor antigens, lower CTLA4 and PD1 expression was detected in the 15×19 CAR group compared to the NT and conventional CAR groups." (PMID 36618357, 2022). "In PDAC, anti-CTLA-4 antibody can block the interaction between CTLA-4 and B7, block the inhibitory signal, and down-regulate the immune system, to induce the host’s inhibitory effect on tumor and produce a lasting anti-tumor effect." (PMID 35965504, 2022). "Nevertheless, because the mechanistic role of atezolizumab is restricted to tumor recognition by T cells, the application of our model to other ICI therapies, such as anti–PD-1 and anti–CTLA-4 therapies, remains to be tested." (PMID 36119066, 2022). "Immune checkpoints, such as PD-L1, PD-1, and CTLA-4, by escaping immune surveillance, play a key role in tumor progression and influence the survival of patients with solid tumors." (PMID 36612211, 2022). "In a separate study, the microbiome was shown to drive anti-tumor responses to CTLA-4 blockade in mice." (PMID 35474500, 2022). "A study reported that CTLA-4 was positively expressed in all TILs and tumor cell cytoplasm, and that high expression of CTLA-4 in tumor tissues was related to a worse prognosis, and CTLA-4 of TIL was only associated with PFS." (PMID 36612259, 2022). "While PD-L1 is more expressed in the tumor cells, the expression of CTLA-4 and IDO conversely appear in the lymphoid cells except for PD-1 which is exclusively in the LCs." (PMID 36104728, 2022). "As expected, DEGs that were upregulated in T cells from tumor tissues, such as CTLA4 and TIGIT, were enriched for exhausted T cell functions." (PMID 36104333, 2022). "CTLA-4 is constitutively expressed on Tregs and is highly expressed in the tumor microenvironment, especially in Tregs." (PMID 36341333, 2022). "Inhibitory immune checkpoint molecules, including PD-1, CTLA4, and LAG3, are abundantly expressed on the surface of tumor-infiltrating lymphocytes, thus causing susceptibility to inhibitory signals from the TME." (PMID 36292781, 2022). "ICB blocks the inhibitory receptors such as PD-1/PD-L1 and CTLA-4, allowing effector T cells to attack the tumor." (PMID 35154149, 2022).
tumor (continued). "The PEGylated CMS@GOx + NIR + anti-CTLA4 group displayed the most superior curative effects, which not only ablated primary tumor but also prominently suppressed the distant tumor growth." (PMID 36348441, 2022). "CircRNAs regarding anti-CTLA-4 resistance are rare by comparison, but there are reports of circRNAs targeting CTLA4 via ceRNA(competing endogenous RNAs) mechanisms to regulate tumor tumorigenesis." (PMID 35615158, 2022). "Targeting adenosine production by CD73 blockade combined with PD-1 or CTLA-4 inhibition promotes tumor regression in a manner dependent on IFN-γ and CD8+ T cells." (PMID 36713558, 2022). "Whereas TTFields treatment alone did not affect the level of cytotoxic CD8+ T lymphocytes (CTLs) in the tumor, significant elevation was displayed in both groups treated with anti-PD-1/anti-CTLA-4." (PMID 36430552, 2022). "Analysis of T-cell infiltration by flow cytometry demonstrated that only anti-CTLA-4 repressed regulatory T cells, which are well described promoters of tumor progression." (PMID 35339889, 2022). "The development of ICI therapy such as anti-PD1 and anti-CTLA4 has revolutionized cancer therapy and resulted in long-lasting tumor responses in patients with a variety of cancers." (PMID 35654823, 2022). "By immunohistochemistry, we detected expression of PD-1 and CTLA-4 on paraffin sections of tumor samples." (PMID 35628262, 2022). "Differential expression in various tumor types influences patient prognosis, which is often associated with coexpression with immune checkpoint inhibitors, such as TIM-3, PD-1 and CTLA-4." (PMID 36077354, 2022). "CAF-S1 subset also can enhance the expression of PD-1 and CTLA-4 at the surface of CD4+ CD25+ FOXP3+ T lymphocytes to participate in the formation of immunosuppressive environment within tumor mass." (PMID 36324128, 2022). "This study also found that PD-1/PD-L1 expression on TAMs and CTLA-4 expression on CD8+ T cells was increased in the presence of CSF-1/CSF-1R blockade, and the combination of PD-1 or CTLA-4 antagonists resulted in more significant tumor regression." (PMID 35874717, 2022). "The additional of both anti-PD1 and anti-CTLA4 therapy improved STING-mediated tumor clearance from 50% to 80%." (PMID 36700206, 2022). "In the local tumor microenvironment, CTLA-4 expression in Tregs upregulates Ido-1 in DCs, which reciprocally promotes Treg activation." (PMID 36419183, 2022). "Immune checkpoint therapies (ICT), such as those mediated by anti-PD-1 or CTLA-4 antibodies, have shown promising long-lasting effects on certain cancer types by activating T cell-mediated anti-tumor immunity." (PMID 35013322, 2022). "Anti-CTLA-4 antibody enhances IL-36 stimulated anti-tumor activity by consuming Tregs, leading to increased CD4+ and CD8+T cells proliferation and IFN-γ levels." (PMID 35874717, 2022). "Immune checkpoint blockade targeting PD-1/PD-L1 and CTLA-4, alone or in combination, confers significant clinical benefits in multiple tumor types, including melanoma." (PMID 35316223, 2022). "ICIs increase anti-tumor immunity by blocking intrinsic downregulators of immunity, such as cytotoxic T lymphocyte antigen 4 (CTLA-4), programmed cell death protein-1 (PD-1), and its ligand programmed cell death-ligand 1 (PD-L1)." (PMID 35693941, 2022). "Other studies showed that the expression of immune checkpoint related proteins such as PD-1 and cytotoxic T lymphocyte associated antigen-4 (CTLA-4) is increased in POLE-mutated EC, and the number of tumor-infiltrating T cells is high." (PMID 35780178, 2022). "Combination therapy is also suggested due to the intricacy of the tumor microenvironment and the modulation of the immune response, particularly when anti-PD-1 and anti-CTLA4 therapy together show promise efficacy on rGBM." (PMID 36146527, 2022).
tumor (continued). "In this context, it has been previously shown that the combination of anti-CD40 and anti-CTLA-4 antibodies accompanying a liposomal peptide or adenoviral vaccine considerably enhanced the CTL responses against tumor cells." (PMID 36091050, 2022). "What’s more, the results of combination therapy showed that compared with PD-1 antibody therapy alone, the expression of PD-L1 and LAG3 in tumor tissues were markedly decreased, and the expression of CTLA-4 was significantly increased." (PMID 36160005, 2022). "In this way, in a preclinical trial in mice with malignancies, it was discovered that the tumor size and progression were dramatically reduced after the combination of anti-CTLA-4 monoclonal antibodies with HPV E6/E7-specific vaccinations." (PMID 36276117, 2022). "The analysis presented that expression of CD4+ T cells in residual tumors and IFN-γ generation in response to tumor cells were considerably higher in mice treated with anti-CTLA-4 than in the control group." (PMID 35392976, 2022). "COL4A1 expression was also significantly correlated with the expression levels of T cell exhaustion marker genes such as PDCD1, CTLA4, LAG3, and HAVCR2 in all the four tumor types with only two exceptions (CTLA4 in SKCM and LAG3 in STAD)." (PMID 35455650, 2022). "The blockade of CTLA-4 signaling promotes T-cell activation and proliferation, henceforth contributing to a T-cell-mediated immune response against tumor cells." (PMID 35160275, 2022). "These expression levels of PD-1, PD-L1, and CTLA-4 in tumor tissue are currently used as predictive markers for immune response." (PMID 36438489, 2022). "Their hydrogel‐based system showed that embedding autologous tumor and lymph node cells together generated personalised immune‐competent PDOs that recapitulated clinical responses to ICIs targeting PD‐1 and CTLA‐4 in 6 of 7 patients." (PMID 35782339, 2022). "Studies show that increased infiltration of immune cells into tumor masses and high expression levels of PD-1/PD-L1 and CTLA-4 correlates with a favorable prognosis of BC." (PMID 35528236, 2022). "Alongside TNFRSF4/OX40 and TNFRSF9/4-1BB, we selected a number of markers of tumor-resident Tregs (CTLA4, ICOS, TIGIT, and FOXP3) and performed k-means clustering for all UPS, MFS, and DDLS samples in the TCGA." (PMID 35558159, 2022). "Of note, a considerable and durable T cell-mediated suppression of tumor growth was observed when PTPN6 knockdown of OT-I T cells was combined with anti-PD-1 and cytotoxic T-lymphocyte-associated protein 4 (CTLA-4) immunotherapy." (PMID 35957898, 2022). "The accumulated FAs can limit anti-CTLA-4 activity and inhibit tumor-specific and memory T cell infiltration into the tumors." (PMID 36199579, 2022). "In this murine model, anti-PD-1 and CTLA-4 therapy in combination with chemotherapy reduced tumour growth." (PMID 36531051, 2022). "We observed that both anti-PD-1 and anti-CTLA-4 weakly but significantly reduced tumor growth in a similar manner." (PMID 35339889, 2022). "Tumor-associated double positive expanded clonotypes frequently displayed a Tem phenotype and expressed elevated exhaustion markers PDCD1, TIM3, LAG3 and CTLA4 similar to tumor-restricted CD8+ expanded clonotypes." (PMID 36185254, 2022). "By breaking the interactions, CTLA-4/PD-1/PD-L1 blockades up-regulate T-cell activity and strengthen anti-tumor immune response." (PMID 36698407, 2022). "For the tumor cells, there were 5 (56%, PD-L1), 0 (0%, PD-1), 0 (0%, CTLA-4), 0 (0%, IDO) cases showed positive IHCs staining." (PMID 36104728, 2022). "High CD155 expression by tumor cells was associated with PD-1+ CD8+T cells and poor response to anti-PD-1, and CD155+PD-L1− tumors exhibited a poor response to anti-PD-1/CTLA-4 therapy." (PMID 33810032, 2021). "Anti-CTLA4 antibodies block the CTLA4 molecules enhancing the anti-tumor immune response via inhibiting Treg-mediated immunosuppression in HPDOX." (PMID 34178691, 2021).
tumor (continued). "And antibody targeting this subset can enhance the effect of anti-CTLA4 checkpoint therapy to block the tumor growth and metastasis." (PMID 33648605, 2021). "PI3K inhibition combined with anti-PD-1 and anti-CTLA-4 significantly inhibited tumour growth and increased durable DC, NK cell and CD8+ T-cell responses compared to ICB alone in mouse models of this carcinoma subtype." (PMID 34944851, 2021). "We evaluated their anti-tumor efficacy when used as single agents or in combinatorial treatments with anti-CTLA-4 mAbs in in vitro co-cultures of hPBMCs with tumor cells, by measuring tumor cell lysis and IL-2 and IFNγ cytokines secretion by lymphocytes." (PMID 35008285, 2021). "Since the approval of Ipilimumab by the FDA in 2011, anti-CTLA-4 and anti-PD-1/L1 have demonstrated efficacy in various tumor types." (PMID 34692696, 2021). "Programmed cell death protein 1 (PD-1/PDCD1), programmed cell death 1 ligand 1 (PD-L1/CD274), and cytotoxic T lymphocyte antigen 4 (CTLA-4) are vital immune checkpoints that play important roles in tumor immune escape." (PMID 34938665, 2021). "Immune checkpoint proteins—especially PD-1, PD-L1, cytotoxic T lymphocyte-associated protein 4 (CTLA-4), and B7 homolog 3 (B7-H3) —have immunosuppressive characteristics that are up-regulated in the GBM TME, which contribute to tumor cell immune escape." (PMID 34248623, 2021). "Our study clarified the prognostic value of several immune checkpoint regulators in KIRC, revealing a CTLA4/miR-20b-5p axis in the control of immune cell infiltration in the tumor microenvironment." (PMID 34336706, 2021). "The blockade of the CTLA-4 signaling with monoclonal antibodies leads to an enhancement of the antitumor immune response, meaning that it has become a potential tumor immunotherapy strategy and is currently undergoing a number of clinical investigations." (PMID 34525966, 2021). "The blockade of inhibitory receptors (CTLA-4 and PD-1) with specific mAb results in the activation of cancer patients’ T lymphocytes and tumor rejection." (PMID 33419027, 2021). "This has been attributed in large parts to the blockade of immune checkpoints either on tumor cells (PD-L1) and Teff (PD-1, CTLA-4)." (PMID 33430105, 2021). "We observed increased expression of the immune checkpoints PD-1, PD-L1, CTLA-4, and CD86 (CD28L), the expression levels of which associated with antitumor efficacy and tumor regression." (PMID 34461854, 2021). "CTLA-4 blockade would result in regulatory T cell depletion, T cell enhancement and tumour reduction." (PMID 33917882, 2021). "A preclinical study demonstrated that the combination of a CSF-1R inhibitor with PD-1 or CTLA4 antagonists elicited tumor regression, while the single use of PD-1 or CTLA4 inhibitors showed limited efficacy." (PMID 33802565, 2021). "While the presence of ICOS+ TA-Tregs in TILs were correlated with a poor prognosis in human tumors, effector CD4+ICOS+ T cells were found to be enriched in the peripheral blood and tumor tissues of patients treated with anti-CTLA-4 antagonistic mAbs." (PMID 33924428, 2021). "CTLA-4 was found to be expressed on CTLs isolated from several tumor types, where it contributes to suppress host immune surveillance." (PMID 34681881, 2021). "With recent developments in cancer treatment, the prominent anti-tumor effects of ICPIs, such as anti-CTLA4 and anti-PD-1 antibodies, have been demonstrated worldwide." (PMID 34204302, 2021). "Based on the information above, people have successfully activated T cells in some tumor cells by using monoclonal antibodies which against PD-L1/CTLA-4 or PD-L1 receptors." (PMID 34858852, 2021). "The only exception was the combined application of the anti-CTLA-4 and the anti-PD-1 molecules which significantly thwarted the growth of the tumor clones in vitro." (PMID 34208396, 2021). "Monoclonal antibodies targeted PD-1/PD-L1 (B7-H1) or B7-2/CTLA-4 pathways have shown promise to induce durable tumor regressions in various tumors." (PMID 34537809, 2021).